INS (insulin)
Diseases named in the same sentence as INS in open-access papers (continued):
Sharing a sentence is not in itself a finding about the gene and the disease.
edema (11 papers, 2006 to 2025). An abnormal accumulation of fluid beneath the skin, or in one or more cavities of the body. "When TZDs are combined with insulin therapy, the incidence of peripheral edema is approximately 15 to 16% as compared with insulin alone which is 5 to 7% [35•]." (PMID 31776781, 2019). "Our study demonstrated that insulin alleviated pulmonary edema and enhanced AFC by increasing the expression of ENaC that dependent upon PI3K/Akt pathway by inhibition of Nedd4-2." (PMID 22458687, 2012). "Oedema has been accepted as an uncommon complication occurring after initiating or intensifying the insulin treatment." (PMID 21274337, 2010). "In one study the absorption of subcutaneous administrated insulin was significantly lower and delayed in patients with generalized subcutaneous oedema." (PMID 16790078, 2006). "This can alter the pharmacokinetic profile of insulin, for example, insulin absorption in patients with severe oedema, which may significantly delay insulin absorption." (PMID 30116732, 2018). "In the current study, our results showed that LPS-induced pulmonary inflammation, pulmonary edema, increase in insulin level and alveolar cell injuries, and LPS-induced reduction of SP-A expression were markedly compromised by GLP-1 analogue liraglutide both in vivo and in vitro." (PMID 29950925, 2018). "Interestingly, many of the described patients with insulin-induced oedema were substantially underweight, with the most dramatic presentation occurring in the underweight patients, a finding similar to our two cases." (PMID 21274337, 2010).
Encephalopathy (11 papers, 2014 to 2025). Encephalopathy is a term that means brain disease, damage, or malfunction. "Insulin, a hormone essential for regulating blood sugar levels, has been linked to AD and encephalopathy in various ways." (PMID 40491970, 2025). "Of the 18 patients with baseline encephalopathy in the insulin group, only 5 showed resolution, compared to 10 of 10 in the SGLT2i group (p < 0.01)." (PMID 40444235, 2025). "Based on the reference and keyword analysis, researchers used to focus on “apoptosis”, “insulin resistance”, “encephalopathy”, “IFN-γ” related to AIT during the past 20 years." (PMID 36032148, 2022). "Finally, encephalopathies, acting simultaneously in both the periphery and central nervous system, BPC 157 counteracted stomach and liver lesions and various encephalopathies in NSAIDs and insulin rats." (PMID 37242459, 2023). "In addition, plasma amino acids, ammonia, insulin, and clinical grading of encephalopathy were lower in vegetable protein diet compared with animal diet." (PMID 31528306, 2019). "Based on typical laboratory findings such as hyperglycemia, ketonuria, ketonemia, metabolic acidosis and clinical features such as vomiting and encephalopathy, a diagnosis of DKA was considered and treatment with intravenous fluids and insulin was started." (PMID 24637313, 2014). "However, no improvement in encephalopathy occurred in spite of intravenous fluids and insulin therapy." (PMID 24637313, 2014). "Finally, for encephalopathies therapy (see Chapter Nerve-Nerve), acting simultaneously in both the periphery and central nervous system, BPC 157 counteracted various encephalopathies and stomach and liver lesions in non-steroidal anti-inflammatory drugs (NSAIDs)-rats and insulin-rats." (PMID 38675421, 2024).
Erythema (11 papers, 2014 to 2026). Redness of the skin, caused by hyperemia of the capillaries in the lower layers of the skin. "Erythema, pruritus, and lipohypertrophy are relatively common problems associated with insulin injections." (PMID 27738545, 2016). "Problems associated with insulin injections, including erythema, pruritus and lipohypertrophy, are relatively common and often mild and transient in their severity and duration respectively." (PMID 25298886, 2014). "Case 8: This patient is a 52-year-old male with poorly controlled T2DM who presented with periumbilical pain, swelling, and erythema at his regular insulin injection site." (PMID 38646389, 2024). "The most commonly reported (≥5 % of patients) treatment-emergent adverse events were nasopharyngitis, headache, elevated blood insulin, diarrhea, injection-site erythema, pharyngitis, arthralgia, fatigue and injection-site reaction." (PMID 25994179, 2015). "Complications relating to insulin injections, including erythema, pruritus and indurations, are relatively common and can interfere with metabolic control (for example, through impaired absorption of insulin)." (PMID 25298886, 2014). "Changes that may occur following insulin administration are lipohypertrophy/lipoatrophy at the injection site, allergic reactions, pruritus, induration of the integument, erythema, calcifications." (PMID 37606477, 2023).
glycogenosis (11 papers, 2012 to 2025). "It is likely that dysregulation of the closely interrelated carbohydrate and lipid metabolic pathways in the liver can cause glycogenosis in this setting when insulin-mediated pathways are bypassed, leading to shunting of substrates from one path to another." (PMID 37047105, 2023). "It has been shown in insulin-deficient rats given a single dose of insulin that glycogenosis persist for a substantial period after blood glucose returned to their initial elevated (insulin-deficient) values." (PMID 23039762, 2012). "Other risk factors for developing euglycemic DKA include recent use of insulin, pregnancy, heavy alcohol consumption, chronic liver disease, glycogen storage disease, and decreased calorie intake." (PMID 35282610, 2022). "In liver, apelin exposure also promotes glycogenosis through the insulin signaling pathway, suggesting this response may be latent activity of DCA although hallmarks of excessive hepatic glycogen storage are no longer present at this point." (PMID 38764585, 2024). "We detected the translocation of GLUT 4 to the cell membrane in CCT - a process that is regulated by insulin as well - thus providing a link between deregulation of insulin signaling and development of glycogenosis and lipogenic phenotype of tubular epithelium also in humans." (PMID 25948777, 2015).
hearing loss (11 papers, 2013 to 2025). "Our findings underscore the importance of individuals with insulin resistance taking proactive measures to prevent hearing loss." (PMID 38464969, 2024). "Mice with Nnt mutations exhibit impaired insulin secretion, which is also known to increase risk of hearing loss." (PMID 36656851, 2023). "Because IGF‐1 is the key effector of growth hormones and inhibits hair cell apoptosis, we speculate that chronic suppression of IGF‐1 signalling due to reduced blood insulin levels can contribute to growth failure and hearing impairment in PFIC1 patients and Atp8b1 mutant mice." (PMID 40851490, 2025).
hypercoagulability (11 papers, 2015 to 2024). "The prevalence of unsupervised hormone use among transgender people ranged between 29% and 63% in New York City and Ontario, and was associated with health risks, such as hypercoagulability and decreased insulin sensitivity." (PMID 36225147, 2022). "It is however clear that there is some causal relationship between increased serum insulin levels and increased fibrinogen levels and a possible state of hypercoagulation." (PMID 25774201, 2015). "An increase of catecholamines can lead to abnormalities in insulin and platelet factors thus also increasing another CHD hallmark namely, Hypercoagulability." (PMID 35252372, 2022). "Increased insulin sensitivity decreases serum levels of platelet factors and thus reduces the potential for hypercoagulability." (PMID 27942693, 2017).
Laron syndrome (11 papers, 2011 to 2024). Laron syndrome is a congenital disorder characterized by marked short stature associated with normal or high serum growth hormone (GH) and low serum insulin-like growth factor-1 (IGF-I) levels which fail to rise after exogenous GH administration. "In addition adult patients with Laron syndrome (inactivating mutations in the GH receptor) remained relatively insulin sensitive (calculated by HOMA-IR), despite an obese phenotype." (PMID 21283519, 2011). "Another classic genetic model of increased lifespan in mammals is the growth hormone receptor (GHR) knock-out mouse, as well as its corresponding genetic defect in humans (Laron syndrome), which is characterized by extreme insulin sensitivity and protection to cancer." (PMID 30926763, 2019). "Similarly, humans with Laron’s syndrome are exquisitely insulin sensitive despite increased adiposity." (PMID 28713554, 2017).
lung fibrosis (11 papers, 2013 to 2025). "We found that the MAPK signaling pathway, insulin resistance, and lung fibrosis-related genes were upregulated." (PMID 37175790, 2023). "A quantification of lung fibrosis with Metamorph® software also showed lung fibrosis was enhanced by repeated insulin administrations in the ND mice." (PMID 31133649, 2019). "Inhaled micronized insulin, after having been registered in the US, was withdrawn because of side effects and adverse events – most notably respiratory insufficiency and lung fibrosis." (PMID 24348585, 2013). "Hence, AE alleviated pulmonary fibrosis by improving insulin resistance and suppressing TGF-β expression." (PMID 35115954, 2021). "Significantly enriched KEGG pathways included the MAPK signaling pathway, insulin resistance, TNF signaling pathway, lung fibrosis, TGFβ receptor signaling, pre-NOTCH Transcription and Translation, signaling by NOTCH, canonical and noncanonical TGFβ signaling." (PMID 37175790, 2023). "Studies on FAM13A regulatory mechanisms have moved from human COPD, fibrosis of the lung, and NSCLC, to insulin sensitivity, adipocyte differentiation, and proliferation, and the correlation between the hypoxic state and other aspects." (PMID 34672860, 2021). "The intranasal administration of insulin enhanced TGF-β1 expression in the bronchial epithelium and lung fibrosis." (PMID 31133649, 2019).
primary aldosteronism (11 papers, 2010 to 2025). An endocrine disorder characterized by excessive production of aldosterone by the adrenal glands. "In patients with primary aldosteronism, after treatment with adrenalectomy or a mineralocorticoid receptor antagonist for primary aldosteronism, the insulin response to glucose increases, and insulin clearance decreases." (PMID 34959901, 2021). "Aldosterone also mediates the downregulation of phosphoenolpyruvate carboxykinase 1, perilipin, adiponectin, C1Q and the collagen domain in visceral adipose tissue, resulting in lower adiponectin levels and reduced insulin sensitivity in patients with primary aldosteronism." (PMID 40296149, 2025). "Another study that aimed to observe the change in glucose tolerance and insulin sensitivity after the treatment of primary aldosteronism observed the rapid and long-term restoration of insulin sensitivity both in patients who underwent surgery and in those who were subjected to drug therapy." (PMID 37628857, 2023). "Furthermore we showed that hemin improved insulin-signaling/glucose metabolism in deoxycorticosterone-acetate (DOCA) hypertension, a model of primary aldosteronism, suggesting a role of the HO system against dysfunctional glucose metabolism in aldosteronism." (PMID 20508722, 2010).
prion disease (11 papers, 2011 to 2023). A transmissible disease that is caused by a protein that is able to induce abnormal folding of normal cellular proteins, leading to characteristic spongiform brain changes, which are associated with neuronal loss without an inflammatory response. "Many observations suggest a possible association between insulin signaling and prion disease." (PMID 26658276, 2015). "This gene is also involved in facilitating the calcium flow in cardiomyocytes during systole, regulating glucose-dependent insulin secretion, muscle size, metabolic pathways of prion disease, and the calcium signaling pathway." (PMID 37627391, 2023). "In several prion diseases infection of the Islet of Langerhans is reported as well as altered levels of pancreatic hormones in serum including insulin and glucagons suggesting that these endocrinopathies are associated with prion infection of the endocrine system." (PMID 22174765, 2011).
renal carcinoma (11 papers, 2013 to 2026). A carcinoma arising from the epithelium of the renal parenchyma or the renal pelvis. "By contrast, GRB10 also acts as a tumor suppressor by negatively regulating phosphatidylinositol 3-kinase and insulin signaling, and is silenced in association with promoter methylation in renal cancer." (PMID 27977763, 2016). "Insulin and insulin-like growth factors were reported to play important roles in the progression and development of tumor, including renal cancer." (PMID 35572505, 2022). "Alcohol’s protective effect for renal cancer is thought to be mediated by an increase in insulin sensitivity, because light to moderate alcohol consumption has been associated with improved insulin sensitivity." (PMID 24881324, 2013). "In conclusion, we showed that IGFs and insulin may play a stimulatory role for renal cancer cells, thus they can possibly affect renal cancer tumorigenesis and progression on cellular level." (PMID 30929166, 2019).
respiratory infections (11 papers, 2014 to 2025). "Before the advent of CFTR modulators, CFRD management consisted in the early introduction of insulin in order to reduce the effects of a catabolic state on respiratory infections, lung function and weight loss." (PMID 40688702, 2025). "We found that the risk of respiratory infections was lower when DPP-4 inhibitor therapy was used concomitantly with insulin, relative to the metformin + insulin combination regimen in male T2DM patients (adjusted OR 0.77; 95% CI 0.61–0.98, p = 0.04)." (PMID 37891260, 2023). "Conversely, frequent respiratory infections and exacerbations can also negatively affect insulin sensitivity and body composition." (PMID 37720540, 2023). "Positive effects for the leaf extract and its key phytochemical constituents have been reported on blood pressure, respiratory infections, inflammation, and insulin resistance." (PMID 32911652, 2020). "Additionally, it is reported to have anti-inflammatory and anti-cancer properties, contributing to increased resistance to enteropathogens and respiratory infections, and playing a role in mitigating weight gain and improving insulin sensitivity." (PMID 33668823, 2021). "With regard to each component of respiratory infections as well as each stratum per patient factor (age, gender, and comorbidity), no significant risk of respiratory infections was assessed among DPP-4 inhibitor + insulin users as compared to metformin + insulin users." (PMID 37891260, 2023).
staphylococcus aureus infection (11 papers, 2018 to 2024). An infectious process in which the bacteria Staphylococcus aureus is present. "The down-regulated pathways in the NS versus LS group included “PI3K-Akt signaling pathway” (1.49%), “Protein digestion and absorption” (1.16%), “Insulin resistance” (0.82%), “Complement and coagulation cascades” (0.07%), and “Staphylococcus aureus infection” (0.03%)." (PMID 37233035, 2023). "In the enrichment analysis of KEGG pathways, we found that only six pathways had significantly statistics including neuroactive ligand-receptor interaction, vascular smooth muscle contraction, pancreatic secretion, cGMP-PKG signaling pathway, insulin secretion and staphylococcus aureus infection." (PMID 33691689, 2021). "It was reported that Staphylococcus infection in HFD-fed dogs could lead to the impairment of glucose tolerance through the damages of insulin secretion and insulin sensitivity." (PMID 30563510, 2018).
systemic inflammatory response syndrome (11 papers, 2013 to 2025). SIRS is a serious condition related to systemic inflammation, organ dysfunction, and organ failure. "As key systemic regulators, insulin and glucagon are critical to energy allocation in the disease syndromes relevant to systemic inflammatory response syndrome (SIRS), including ALF." (PMID 35053214, 2022). "The insulin pump therapy was most likely reducing systemic inflammatory response syndrome (SIRS), which is associated with a lower rate of infections in patients on insulin pump therapy at early post-CABG." (PMID 34362176, 2021). "In trauma, systemic inflammatory response syndrome (SIRS), or severe burns, insulin reduces pro-inflammatory mediators (TNF-a, IL-6, CRP, IFN-y, IL-18)." (PMID 39838305, 2025). "For patients undergoing emergency laparotomy, physiological issues such as bowel dysfunction, insulin resistance, fluid shifts, and systemic inflammatory response syndrome (SIRS) can arise even before surgery." (PMID 40291936, 2025). "ein durch ein operationstraumainduziertes Systemic Inflammatory Response Syndrome (SIRS), können unter SGLT-2-Hemmern via veränderter Glukagon-Insulin-Ratio euglykämische Ketoacidosen induzieren, wovor die Food and Drug Administration bereits 2015 warnte." (PMID 38635034, 2024).
Turner syndrome (11 papers, 2008 to 2024). Turner syndrome is a chromosomal disorder associated with the complete or partial absence of an X chromosome. "It was not possible to examine the risk of receiving > 1 prescription for insulin/insulin analogues in children with Klinefelter and Turner syndrome due to the rarity of these anomalies and the small number that were born alive." (PMID 36869270, 2023). "The present study was designed to evaluate the influence of body composition and insulin resistance on postprandial triglyceride levels in women with Turner's syndrome receiving oral versus transdermal estrogen therapy." (PMID 34033286, 2021). "The aim of the present study was to examine the influence of body composition and insulin resistance on the magnitude of postprandial lipemia in patients with Turner's syndrome receiving oral versus transdermal estrogen replacement." (PMID 34033286, 2021). "Twenty-five patients with Turner's syndrome receiving oral or transdermal estrogen replacement were evaluated for body mass index, waist-to-hip and waist-to-height ratios, fasting glycemia, insulin, body composition (dual-energy X-ray absorptiometry), and postprandial lipid metabolism." (PMID 34033286, 2021). "Firstly, clinical studies suggest that GH may be beneficial in non-GH-deficient (non-Turner Syndrome) individuals with visceral obesity, by reducing abdominal fat and improving insulin sensitivity." (PMID 22472028, 2012).